TNF (tumor necrosis factor)
Diseases named in the same sentence as TNF in open-access papers (continued):
Sharing a sentence is not in itself a finding about the gene and the disease.
diabetes (continued). "High glucose upregulated the expression of multiple inflammatory cytokines, including tumor necrosis factor-α (TNF-α), interleukin-1β (IL-1β) and interleukin-6 (IL-6), which might be linked to the pathogenesis of the complications of central nervous system in diabetes." (PMID 29867440, 2018). "Inflammatory biomarkers, such as white cell counts (WBC), C-reactive protein (CRP), tumor necrosis factor-α (TNF-α), and interleukin-6 (IL-6), were showed to be correlated with prevalent and incident diabetes." (PMID 29651306, 2018). "Compared with NC, the levels of serum inflammation indexes like CRP, IL6, IL8, TNF-α, and CCL2 were significantly increased (p < 0.05), while IL10 levels were significantly decreased (p < 0.05) in diabetes groups (MC, WP and SCCOPs-treated groups)." (PMID 29316680, 2018). "Additionally, TNFα may play a pivotal role in the association between HCV infection and diabetes." (PMID 29258547, 2017). "To further investigate the role of TIPE2 in diabetes, we studied the relationship between TIPE2 mRNA expression and the serum concentrations of hsCRP, TNF-α, and IL-6." (PMID 28626770, 2017). "Further, LncRNA NONRATT021972 siRNA decreased blood glucose level and decreased TNF-α, verified by ELISA (P < 0.05), suggesting that inhibition of LncRNA NONRATT021972 attenuated inflammation of STZ-induced diabetes." (PMID 28928602, 2017). "TNF-α induces the generation of various types of mediators, and the expression levels of TNF-α are known to be high in inflammatory diseases and diabetes." (PMID 28584398, 2017). "One of the important pathogenetic mechanisms of beta-cell damage during diabetes is the increased expression of proinflammatory cytokines such as IL-1β, interferon (IFN)-γ, and TNF-α." (PMID 28405188, 2017). "The major risk factors for activation of TB after an extended latent period include contact with an infectious TB patient, HIV co-infection, initiation of an anti-tumor necrosis factor (TNF) treatment, silicosis, and diabetes." (PMID 34993126, 2017). "Expression of TNF-α, IFN-γ, and IL-10 within the islets all enhance NOD insulitis and diabetes development." (PMID 29497709, 2017). "We also found that TonEBP+/− mice had reduced levels of hepatic lipogenic factors, HMGB1, IL-6, and TNF-α expression, as well as reduced macrophage infiltration and proinflammatory cytokines in adipose tissues of HFD/STZ-induced diabetes." (PMID 28798347, 2017). "In line with previous findings, NOD macrophages produced higher protein levels of IL-6 and CXCL-1 (KC) and an upward tendency for TNFα and MCP-1, compared to non-diabetes-prone control C57BL/6 counterparts." (PMID 29095944, 2017). "Activation of these pathways leads to chronic inflammation in target organs with upregulation of inflammation-related molecules such as TNF-α and VAP-1, both of which proved to be elevated in the plasma of patients with diabetes." (PMID 29240802, 2017). "One of these cytokines, tumor necrosis factor (TNF-α), has been investigated since diabetics have elevated levels of it circulating." (PMID 27822481, 2016). "Diabetes-induced p38 MAPK activation promotes the production of inflammatory factors, including TNF-α, IL-1, IL-4, IL-6 and IL-8, by tissues and cells." (PMID 27413117, 2016). "Consistent with studies in healthy individuals and patients with diabetes, studies in patients with CKD measured TNFα and reported an increase due to a high AGE diet." (PMID 26938557, 2016). "In comparison with severe diabetes controls, MSC infusion reduced insulitis, decreased pancreatic TNF-α, and increased IL-10 and TGF-β1 expression in NOD mice." (PMID 27905403, 2016). "In patients with diabetes or with high level of glucose, miR-30d could regulate Map4k4 expression to increase the levels of insulin transcription factors, thus promoting the insulin secretion and reducing TNF-α-induced transcription and production of insulin genes." (PMID 28066696, 2016).
diabetes (continued). "In addition, it has been shown that a single high-fat high-calorie meal results in inflammation with increased expression of NFkB and many pro-inflammatory cytokines, including TNF-α which suggests that dietary factors could be a common link between inflammation and diabetes." (PMID 27581604, 2016). "Inflammatory mediators such as TNF-α, IL-6, and CRP, which are elevated in COPD, are also increased in diabetes." (PMID 27335596, 2016). "The progression to diabetes in control NOD mice was characterized by significantly elevated levels of most Teff subsets (IFN-γ+, Th17+, IL-2+, TNF-α+ and CD40+ lymphocytes) in the pancreatic lymph node." (PMID 26674203, 2015). "This contrasts with previous findings in C57Bl/6 mice at later time points after 8 weeks of diabetes, in which we were able to detect increased ICAM-1 mRNA in retinal vessels and enhanced levels of TNFα, IL-6, and IL-1β mRNA in whole-retina homogenates." (PMID 25918731, 2015). "NXT also inhibited the diabetes-induced expression of CAS-3 protein and mRNA, MMP-2/9 and TNFα mRNA, accumulation of carbohydrate macromolecules, and formation of acellular capillaries in the retina." (PMID 25821481, 2015). "Chronic inflammation occurred in the diabetic pancreas accompanied by up-regulation of CCAAT/enhancer-binding protein beta (C/EBPβ) and its targets (TNFα, Il6, CRP, and Fn1) as well as myeloperoxidase (Mpo) and C-X-C chemokine receptor type 2 (Cxcr2)." (PMID 26110898, 2015). "However, TNF-α levels in the diabetes + β-anhdroicaritin group and diabetes + urate group were significantly higher compared with those in the diabetes group (P<0.05), and those in the diabetes + β-anhydroicaritin group were lower compared with those in the diabetes + urate group (P<0.05)." (PMID 25847066, 2015). "Diabetes markedly reduced T-GSH, NP-SH, CAT and SOD, while TBARS, TNF-α and IL-1β levels were increased in the diabetic testis compared to non-diabetic controls." (PMID 26122042, 2015). "The BMI/WHtR 5-category variable was a significantly better discriminator of high triglycerides, low HDL-C, pre-diabetes, high C3, CRP, IL-6, TNF-α and WBC levels compared to BMI, and of leptin compared to WHtR." (PMID 26351521, 2015). "The administration of 1.5 g of NAC/kg/day, via gavage, for 4 weeks after induction of diabetes, increased TAS levels, in plasm, and SOD hepatic tissue activity, and inflammatory biomarkers levels were decreased in serum, for instance, TNF-α and IL-6." (PMID 26694382, 2015). "Increased inflammation due to induction of pro-inflammatory cytokine such as tumor necrosis factor-alpha (TNF-α) and attenuation of anti-inflammatory cytokine such as interleukin 10 (IL-10) contributes to cardiac dysfunction in obese and diabetics." (PMID 25954207, 2015). "We recently demonstrated that IGFBP-3 knockout mice have neuronal characteristics of diabetes and that IGFBP-3 and TNFα have antagonistic actions on apoptosis in retinal endothelial cells." (PMID 24695399, 2014). "Subgroup analyses of the gene expression of Homer1, Homer2, Homer3, IL-1β, and TNF-α between CAD patients and controls by hypertension and diabetes." (PMID 25551602, 2014). "Gene expression array results indicate that although VEGF is upregulated in diabetic retinas along with other angiogenic factors like Ang-2 and TNFα, CCL2 is remarkably upregulated, and this increase is maintained at least up to 8 weeks of diabetes." (PMID 25329075, 2014). "The levels of inflammatory mediators (NF-kB, IL-1β, tumor necrosis factor α, and ICAM-1 etc.)are elevated in the retina in diabetes and leukostasis is increased." (PMID 24479616, 2014). "For IL-1β and TNF-α, there were significant differences between CAD patients and controls in participants of hypertension (p < 0.001 and p < 0.001), diabetes (p = 0.017 and p = 0.025), respectively." (PMID 25551602, 2014).
diabetes (continued). "Higher systemic levels of C-reactive protein (CRP), and soluble receptors of tumor necrosis factor-alpha (TNF-α), sTNF1 and sTNF2, accompany incident diabetes after initiation of HIV antiretroviral therapy." (PMID 24587328, 2014). "COPD patients exhibit elevated levels of inflammatory biomarkers including CRP, TNF-α, fibrinogen, leukocytes, IL-6, and IL-8 suggesting that COPD may be similar to other diseases associated with systemic inflammation including CAD, peripheral arterial disease, osteoporosis and diabetes." (PMID 25480156, 2014). "The enhanced pro-inflammatory burden in diabetic mice is also reflected by the overall increased levels of circulating plasma cytokines (IL-6, IFN-γ, IL-12p70, IL-1β, IL-10, TNFα, OPN and sVCAM-1) after 8 weeks of diabetes." (PMID 23755169, 2014). "Some histological and immunohistochemical alterations for TNF-alpha, iNOS and COX-2 in the diabetic pancreas were also reversed by PTX." (PMID 24991532, 2014). "CRC initiation and promotion by diabetes is due to diabetes-induced increase in growth factors (e.g., insulin, IGF-1) and inflammatory adipo/cytokines (e.g., TNFα, IL-6)." (PMID 25375205, 2014). "Since diabetes leads to increased TNFα and decreased IGFBP-3, increased understanding of the interrelationship of TNFα and IGFBP-3 will likely lead to refined therapies that can promote IGFBP-3 actions, while inhibiting TNFα activities." (PMID 25073020, 2014). "After 12 weeks of diabetes, oat treatment reduced blood glucose levels, HbA1c, all oxidative stress markers, CML, normalized NF-κB activation and TNFα expression." (PMID 23365614, 2013). "Previously, various studies have documented that diabetes enhanced the production of inflammatory mediators such as iNOS, IL6, and TNF-α in the retina." (PMID 23671886, 2013). "A number of proinflammatory cytokines/chemokines including TNF-α, IL-1 and IL-6, and MCP-1 were well documented to involve in the pathogenesis of diabetes mellitus." (PMID 24078930, 2013). "After 12 weeks of diabetes, renal protein and mRNA MCP-1 and ICAM-1 expression, and levels of TNF-α and IL-6, were markedly increased in the DM group, as compared with NC rats." (PMID 23935673, 2013). "Consistent with previous studies, it was demonstrated that TNF-α and NGAL levels were significantly elevated and correlated with the severity of albuminuria in patients with diabetes." (PMID 24250725, 2013). "WB analysis revealed a higher expression of 5-LO, VEGF, TNF-α and RAGE in the retina of diabetic rats on HFD than in controls and diabetics fed on a normal diet." (PMID 23587252, 2013). "Intravitreal administration of the ERK1/2 inhibitor U0126 prior to induction of diabetes decreased ERK1/2 activation, attenuated diabetes-induced upregulation of MMP-9, iNOS, IL-6, and TNF-α and upregulated TIMP-1 expression." (PMID 23671886, 2013). "It was observed that baseline levels of urinary TNF-α and NGAL were significantly elevated and correlated with the severity of albuminuria in patients with diabetes." (PMID 24250725, 2013). "NF-κB has been localized to the inner nuclear layer and ganglion cells of the retina, and NF-κB-regulated inflammatory gene products are reported to be upregulated in the retinas during diabetes such as cyclooxygenase-2, iNOS, ICAM-1, and TNF-α." (PMID 23671886, 2013). "Tumor necrosis factor-alpha (TNF-α) is overexpressed in the adipose tissues of patients with diabetes and was identified as the first molecular link between inflammation and diabetes." (PMID 23592916, 2013). "This beneficial effect of targeting TNF-α is in agreement with a recent study that pharmacological inhibition of TNF-α by etanercept, a TNF-α antagonist, blocks behavioral signs of diabetic neuropathic pain." (PMID 23735240, 2013). "Diabetes abrogates the protective effect of female gender, since diabetic women showed increased BMI, WC, small HDL-c, VEGF, uric acid, TNF-α and hsCRP, as well as reduced adiponectin, when compared with non-diabetic." (PMID 23570342, 2013).
diabetes (continued). "Therefore, PKC-β2 and NADPH oxidase interplay may play critical roles in mediating cellular damage in situations associated with increased TNF-α production, such as AMI, heart failure, and diabetes, as well as during cardiac surgery using cardiopulmonary bypass." (PMID 24396568, 2013). "For example, in microvascular endothelial cells, FOXO1 is induced in vivo by diabetes-enhanced TNF-α and also induces expression of TNF-α levels in these cells." (PMID 22454632, 2012). "TNF-α, IL-6, MCP-1 and CRP are elevated in obese individuals, and predict diabetes and cardiovascular disease." (PMID 22984471, 2012). "Regarding to TNF-alpha, we found an increase in the number of TNF-alpha-positive cells after 6 and 12 months of diabetes induction." (PMID 22611374, 2012). "However, in two of those other reports, the observation of increased retinal TNF-α in response to diabetes was made after 1 or 2 weeks of diabetes and such increase could have been secondary to the initial acute metabolic imbalance after the induction of diabetes or to streptozotocin toxicity." (PMID 22615852, 2012). "Immunohistochemical procedures for MMP-2, MMP-9, TNF-α, IL-1β, IL-6, RANKL, and RAGE were performed in rats after 1, 3, 6, 9, and 12 months of diabetes induction." (PMID 22611374, 2012). "This up-regulation of death receptor expression, coupled with increased TNF-α secretion, could promote endothelial cell apoptosis, which is likely to contribute to coronary arterial endothelial dysfunction and the development of ischemic heart disease in diabetes." (PMID 21816064, 2011). "The proinflammatory cytokines TNF-α and IL-6 have been shown to both suppress and antagonize the action of APN in diabetes." (PMID 21912612, 2011). "Results also suggest a complex role for TNFα in the regulation of VCAM-1 expression, being protective under basal conditions but promoting endothelial activation in response to diabetes." (PMID 20856927, 2010). "The existence of chronic inflammation in diabetes is mainly based on the increased plasma concentrations of C-reactive protein (CRP), fibrinogen, interleukin-6 (IL-6), interleukin-1 (IL-1), and TNFα." (PMID 20634940, 2010). "The present communication has reviewed some recent studies on diabetes-induced endothelial dysfunction and has discussed the important roles of arginase, PKC and TNF in this complicated pathological condition." (PMID 20877687, 2010). "Here we investigated the impact of diabetes and dyslipidemia on VCAM-1 expression in mouse retinal vessels, as well as the potential role of tumor necrosis factor-α (TNFα)." (PMID 20856927, 2010). "Results also suggest a complex role for TNFα in the regulation of VCAM-1 expression, being protective under basal conditions but pro-inflammatory in response to diabetes." (PMID 20856927, 2010). "The present study investigated early retinal endothelial activation in diabetes and/or dyslipidemia by assessment of VCAM-1 expression in mouse retinal vessels, as well as the potential role of TNFα." (PMID 20856927, 2010). "For a more systemic indication of endothelial activation in response to diabetes, we measured soluble VCAM-1 (sVCAM-1) in plasma from wt, ApoE−/− and ApoE−/−/TNFα−/− mice." (PMID 20856927, 2010). "To establish a role for TNF-α in the pathogenesis of signature lesions in diabetic retinopathy and to address the question whether the demonstrated effects are only due to its transient overexpression in early diabetes, we used a long-term mouse model of diabetic retinopathy." (PMID 19641635, 2009). "Patients with diabetes demonstrate high expression of TNF-α inskeletal muscle and in plasma, and it is likely that adipose tissue, whichproduces TNF-α, is the main source of the circulating TNF-α." (PMID 19148295, 2008). "In another study, TNFα expression within the pancreas prevented diabetes in NOD mice, while systemic treatment of TNFα in adult NOD mice decreased insulitis as well as the incidence of diabetes." (PMID 18380898, 2008).
diabetes (continued). "One scenario might be that a combination of early diabetes onset and late TNFα availability would lead to enhanced physiological stress to β-cells, preventing them from producing transgenic TNFα and therefore reducing the possibility of TNFα induced apoptosis of autoreactive T cells." (PMID 23675028, 2007). "Klotho, which mitigates diabetes-induced elevation of serum creatine kinase-muscle/brain (CK-MB) and LDH, cardiac fibrosis, cardiomyocyte apoptosis, and cardiac dysfunction, also inhibits NLRP3 activation and TNF-α, IL-1β, and IL-18 expression." (PMID 41399377, 2026). "This study, based on KEGG pathway enrichment analysis, further confirmed that the main pathways through which diabetes is intervened involve lipid and atherosclerosis, the PI3K-Akt signaling pathway, and the TNF signaling pathway, which is consistent with previous mechanistic understandings." (PMID 41515064, 2026). "This contrasts with previous studies reporting marginally detectable TNFα levels in GCF of insulin-dependent diabetics, regardless of periodontal severity." (PMID 41280935, 2025). "Other reports similarly noted that hyperglycemia and diabetes are associated with profound lymphopenia and elevated CRP, IL-6, TNF-α, and PCT compared with non-diabetic patients." (PMID 41156159, 2025). "Elevated levels of serum reactive oxygen species, interleukin (IL)-1, IL-6, tumor necrosis factor (TNF)-α, and C-reactive protein (CRP) have been observed in patients with established type 2 diabetes mellitus (T2DM), indicating their potential role in periodontal tissue destruction." (PMID 40283677, 2025). "The results of the moderator analysis indicated that NSE, IL‐6, MDA, and TNF‐α did not exhibit a moderating effect on diabetes‐related cognitive impairment." (PMID 39829127, 2025). "Following adjustment for age, sex, triglyceride levels, diabetes, and hypertension, a covariate variance analysis revealed significant differences between these groups with respect to plasma levels of TWEAK, TNF-α, IL-10, and IL-4 (PTWEAK = .017, PTNF-α < .001, PIL-10 = .010, PIL-4 = .016)." (PMID 40629651, 2025). "This meta-analysis evaluates the effects of probiotics on C-reactive protein (CRP), tumor necrosis factor-alpha (TNF-α), interleukin-6 (IL-6), malondialdehyde (MDA), total antioxidant capacity (TAC), glutathione (GSH), and nitric oxide (NO) in patients with diabetes." (PMID 40123937, 2025). "Although there were correlations between cognitive performance and various cognitive scores, IL‐6, MDA, NSE, VCAM‐1, and TNF‐α did not play a mediator role in the neuropathology of diabetes‐related cognitive impairment." (PMID 39829127, 2025). "NDUFS1 exhibits a negative correlation with IL6 and TNF, suggesting a potential link to inflammatory processes in the context of diabetes or sarcopenia." (PMID 40869253, 2025). "Although TNF‐α was found to have a direct effect on naming functions (p = 0.040), it did not have a moderating function in diabetes‐related cognitive impairment (p = 0.43)." (PMID 39829127, 2025). "Biomarkers like interleukin-6 (IL-6), C-reactive protein (CRP), and tumor necrosis factor-alpha (TNF-α) are related to inflammation and may serve as indicators of cardiac inflammation in diabetes." (PMID 39129285, 2025). "Diabetes worsens periodontitis via ↑ inflammatory response, impaired bone metabolism, oxidative stress, and AGE–RAGE signaling; GLP‐1RAs inhibit NF‐κB and activate AMPK, suppressing IL‐6, IL‐1β, and TNF‐α." (PMID 41328144, 2025). "Similarly, cytokines such as TNF-α, IL-6, and CRP are elevated in obesity and diabetes, further enhancing oxidative stress and inflammation." (PMID 40243674, 2025). "KCLE also improves diabetes by regulating AKT1, TNF, EGFR, and GSK3β." (PMID 40076380, 2025).